APOA2 (apolipoprotein A2)
Diseases named in the same sentence as APOA2 in open-access papers (continued):
Sharing a sentence is not in itself a finding about the gene and the disease.
lung carcinoma (7 papers, 2019 to 2023). "When combined with other inflammatory markers and tumor markers, APOA2 was successful in diagnosing early-stage lung cancer patients, including NSCLC." (PMID 38067270, 2023). "While there is a substantial number of studies exploring the function of APOA1 in relation to lung cancer, research on the role APOA2 in lung cancer is scarce." (PMID 38067270, 2023). "Nevertheless, a study was conducted to assess tumor and inflammatory markers and their role in diagnosing lung cancer, such as APOA2, an inflammatory marker that was significantly differentiated between non-small-cell lung cancer (NSCLC) patients and controls, with a sensitivity of 89%." (PMID 38067270, 2023). "These contrasting findings around APOA2 and APOA4 within lung cancer subtypes are a testament to the molecular diversity of the disease." (PMID 38067270, 2023).
ovarian carcinoma (7 papers, 2010 to 2023). A malignant neoplasm originating from the surface ovarian epithelium. "The most recent analysis studied a multiple biomarker combination including APOA1 and APOA2 for ovarian cancer." (PMID 38067270, 2023). "The results showed that the most optimal biomarker combination was a panel of five markers: CA 125, HE4, CA 15-3, APOA1, and APOA2, giving a sensitivity of 93.71% and a specificity of 93.63% for detecting ovarian cancer." (PMID 38067270, 2023). "The loss of APOA1, APOA2, and APOA4 was reported in ovarian cancer patients." (PMID 38067270, 2023). "Meanwhile, it has been reported, that APOA2 bears different types of PTM (phosphorylation and acetylation) within initiation center of APOA2 homodimerization in patients with breast and ovarian cancer, which meaningfully prevents proper functioning and embedding of APOA2 into HDL particles." (PMID 34588485, 2021).
pancreatic diseases (6 papers, 2012 to 2026). "It was considered that the alteration of the cleavage of C-terminal of apoA2 homodimers was induced by activation of carboxypeptidases, which were leaked and activated from the microenvironment reflected by pancreatic disorders." (PMID 38261000, 2024). "We have previously reported that specific abnormal processing patterns of the amino acids at the C-terminal ends of apoA2 homodimers are observed in pancreatic diseases." (PMID 32937962, 2020). "Pancreatic diseases were recognized in about 30% of subjects with an apoA2-ATQ/AT level of ≤35 μg/mL." (PMID 32937962, 2020). "Second, actual prevalence rates of PC and other pancreatic diseases in the apoA2-ATQ/AT-negative group could not be evaluated because CECT, MRCP and EUS are too expensive and invasive to perform in all cases." (PMID 32937962, 2020).
breast carcinoma (5 papers, 2016 to 2025). "Certain apolipoproteins play a central role in lipid metabolism, and changes in the expression of ApoA2 occur in malignancies other than breast cancer." (PMID 28210565, 2017). "The patients exhibited significantly lower levels of key apolipoproteins, including apoA-1, apoA-2, apoC-2, and apoC-4, compared to luminal A, luminal B, and HER2-positive breast cancer patients (p-values ranging from 0.004 to 0.057)." (PMID 40430118, 2025).
cognitive decline (5 papers, 2012 to 2025). "Lower ApoA1, ApoA2 and ApoH levels, and higher ApoB/ApoA1 ratio, increased the risk of cognitive decline over two years in cognitively normal individuals." (PMID 22701550, 2012). "In summary, participants with lower ApoA1, ApoA2, ApoH levels or higher ApoB/ApoA1, at Wave 1 had a higher risk of future cognitive decline." (PMID 22701550, 2012).
Cognitive impairment (5 papers, 2012 to 2024). Abnormal cognition is characterized by deficits in thinking, reasoning, or remembering. "After adjusting for other factors, ApoA1 and ApoA2 were found to be associated with cognitive impairment." (PMID 26682220, 2015). "Increased APOA2 expression is associated with cognitive impairment and late-life dementia." (PMID 36834799, 2023). "Moreover, ApoA1 and ApoA2 were independently associated with cognitive impairment and late-life dementia." (PMID 26682220, 2015). "However, after adjusting for age, AS levels, BMI, and comorbidity numbers, only ApoA1 and ApoA2 were found to be possible risk factors of cognitive impairment in older men." (PMID 26682220, 2015). "Subjects with older age, a lower level of ApoA1, and a higher level of ApoA2 might have more possibilities of undergoing cognitive impairment." (PMID 26682220, 2015). "The result presented that ApoA1 and ApoA2 might actually have impacts on cognitive impairment." (PMID 26682220, 2015). "Furthermore, including lipid profile as covariates did not affect the ability of ApoA1, ApoA2 and ApoH levels and ApoB/ApoA1 ratio to predict cognitive impairment." (PMID 22701550, 2012).
liver cancer (4 papers, 2022 to 2024). An epithelial or non-epithelial malignant neoplasm that arises from the liver. "The reactivities of apoA2-ATQ/AT toward esophageal, gastric, colon, and liver cancer were 30% (9/30), 20% (2/10), 30% (9/30), and 20% (2/10), respectively." (PMID 38261000, 2024). "The transcript of APOA2, ENST00000367990.6, is exclusively active in liver cancer across different cancer types, and also specifically expressed in liver tissue across multiple tissue types." (PMID 35473935, 2022).
Stroke (4 papers, 2010 to 2025). Sudden impairment of blood flow to a part of the brain due to occlusion or rupture of an artery to the brain. "Corresponding numbers for stroke were 47 proteins with nominal P < 0.05, three of which, apolipoprotein A-II precursor (APOA2), peptidyl-prolyl isomerase A (PPIA), and insulin-like growth factor binding protein 4 (IGFBP4), have a false discovery rate < 0.05." (PMID 20667078, 2010).
allergic rhinitis (3 papers, 2020 to 2025). Inflammation of the nasal mucous membranes caused by an IgE-mediated response to external allergens. "C3, A2M, APOA1, and APOA2 were also found to be significantly more abundant in nasal mucus in allergic rhinitis patients in our previous studies." (PMID 32266843, 2020).
chronic pancreatitis (3 papers, 2015 to 2026). A chronic inflammatory process causing damage and fibrosis of the pancreatic parenchyma. "A significant reduction in apoA2 was detected not only in PDAC but also in risk diseases of PDAC such as chronic pancreatitis, IPMN and others." (PMID 27673558, 2016). "In addition, a significant reduction in apoA2-ATQ/AT was also detected in chronic pancreatitis, which is considered as a risk disease of PDAC." (PMID 27673558, 2016).
glaucoma (3 papers, 2021 to 2024). Increased pressure in the eyeball due to obstruction of the outflow of aqueous humor. "Similar to our study, APOA1 and APOA2 levels were reportedly elevated in AH in patients with glaucoma shunt devices and corneal endothelial damage." (PMID 35401527, 2022). "Within the African American cohort, APOA1, APOA2, APOA4, and APOD levels were significantly higher among glaucoma patients." (PMID 34602085, 2021).
hyperlipidemia (3 papers, 2010 to 2016). "Sequencing analysis revealed polymorphisms of Apoa2 in TH mice, suggesting Apoa2 as the candidate gene for the hyperlipidemia QTL." (PMID 21167066, 2010). "ApoA2 is responsible for lipid transportation and alteration in the levels of apoA2 isoforms might be associated with hyperlipidemia." (PMID 27673558, 2016). "Some loci observed on chow diets are obscured on the hyperlipidemia background; for example, on a chow diet, the Apoa2 locus on Chr 1 is a major determinant of HDL-cholesterol levels suggesting that gene x diet interactions influence disease susceptibility." (PMID 26694027, 2015). "However, investigation of the correlation between the alteration of apoA2 isoforms and high-density lipoprotein, and hyperlipidemia are important topics for future studies." (PMID 27673558, 2016). "In order to test if Apoa2 could be the Chr 1 hyperlipidemia QTL, we conducted sequence comparison of the coding region between TH and B6 mice." (PMID 21167066, 2010).
schizophrenia (3 papers, 2019 to 2022). A major psychotic disorder characterized by abnormalities in the perception or expression of reality. "A meta-analysis between schizophrenia patients and healthy controls was performed, with the results suggesting four apolipoproteins, APOA1, APOA2, APOC1 and APOC3 (downregulated), and ficolin-3 (upregulated) as potential biomarkers of the disorder." (PMID 35563307, 2022). "In a previous paper, we observed that apolipoprotein A2 was lower in patients with schizophrenia without MetS, unlike patients with MetS." (PMID 33066473, 2020).
Sepsis (3 papers, 2018 to 2023). Sepsis is defined as life-threatening organ dysfunction caused by a dysregulated host response to infection. "Multiple MR analyses also indicated that the Apoa2 gene and protein have a causal relationship with sepsis and related syndromes." (PMID 37511084, 2023). "Through analyzing expression quantitative trait locus (eQTL) and genome-wide association studies (GWAS), colocalization analysis on Apoa2 and sepsis phenotype was conducted by summary-data-based Mendelian randomization (SMR)." (PMID 37511084, 2023). "As a result, Apoa2 protein or mRNA was identified as a target biomarker for H2 with a protective, causal relationship with sepsis." (PMID 37511084, 2023). "Our study indicated the causal relationships between Apoa2 and heart-related outcomes in sepsis." (PMID 37511084, 2023). "From SMR analysis, a colocalization correlation relationship between Apoa2 mRNA and sepsis was identified." (PMID 37511084, 2023). "Our study proposed that APOA2 has promising protective and curative values in sepsis-related lung injury." (PMID 37511084, 2023). "In immunofluorescence (IF) experiments, Apoa2 level was found to be significantly decreased in sepsis mice lung tissue." (PMID 37511084, 2023). "At the same time, our colocalization analysis results showed that mRNA Apoa2 shared common SNPs with sepsis." (PMID 37511084, 2023). "Then, we extracted four SNPs from sepsis datasets to evaluate Apoa2 mRNA effects on two syndromes, pneumonia and heart failure." (PMID 37511084, 2023). "The agitation and inhibition of Apoa2 were indicated to influence sepsis and related syndromes." (PMID 37511084, 2023). "For CLP-induced sepsis, Apoa2′s role requires need further study." (PMID 37511084, 2023). "According to these results, the change in Apoa2 mRNA affected the sepsis outcome." (PMID 37511084, 2023). "The protective effects of Apoa2 mRNA activation in sepsis were validated." (PMID 37511084, 2023). "In addition, our syndrome Mendelian randomization study revealed an increasing probability of sepsis-related syndrome, pneumonia (OR = 1.65) and heart failure (OR = 1.50) due to the Apoa2 gene changes in sepsis." (PMID 37511084, 2023). "At the mRNA level, Apoa2 expression was down-regulated in the sepsis model." (PMID 37511084, 2023). "Regarding protein levels, by using semi-quantitative and quantitative methods, immunofluorescence and Elisa, we found that the trends at the protein level were as follows: Apoa2 was decreased for sepsis and H2 treatment was able to restore the abnormal decrease." (PMID 37511084, 2023). "This could also explain why Apoa2 could affect the progression of sepsis in our analysis." (PMID 37511084, 2023). "In existing studies, the effects of Apoa2 mRNA interventions on sepsis are still unknown." (PMID 37511084, 2023). "H2 interventions would reverse negative changes in Apoa2 in the development of sepsis according to our results." (PMID 37511084, 2023).
AA amyloidosis (2 papers, 2018 to 2023). Secondary amyloidosis is a form of amyloidosis, that complicates chronic inflammatory disorders (mainly rheumatoid arthritis) and is characterized by the aggregation and deposition of amyloid fibrils composed of serum amyloid A protein, an acute phase reactant. "Herein, we employed apolipoprotein A-II (ApoA-II) deficient (Apoa2−/−) and transgenic (Apoa2Tg) mice to investigate the potential roles of ApoA-II in lipoprotein particle formation and progression of AA amyloidosis during APR." (PMID 29618729, 2018). "Recently, it has been shown that Apoa2 knockout mice had less tissue damage and less inflammatory cell infiltration during acute-phase response and may play an important role in the pathogenesis of amyloid A amyloidosis in mice." (PMID 37505703, 2023). "We employed Apoa2−/− and Apoa2Tg mice to explore the mechanism by which ApoA-II influences SAA metabolism and AA amyloidosis." (PMID 29618729, 2018).
Cirrhosis (2 papers, 2023 to 2025). A chronic disorder of the liver in which liver tissue becomes scarred and is partially replaced by regenerative nodules and fibrotic tissue resulting in loss of liver function. "On an opposite trend, sera from patients with cirrhosis were particularly enriched in low-density HDL1 lipoproteins (H1PL, H1CH) and apolipoprotein A2 (HDA2 and TPA2)." (PMID 36834973, 2023).
diabetic retinopathy (2 papers, 2018 to 2024). "Of the differentially expressed proteins, we were particularly interested in APOA2 and CP, which play critical roles in lipoprotein metabolism, inflammation, oxidative stress, apoptosis, and other processes associated closely with the development of diabetic retinopathy." (PMID 29850212, 2018). "Both APOA1 and APOA2 are discussed as biomarkers and treatment targets in diabetic retinopathy (DR), polypoidal choroidal vasculopathy (PCV), and AMD, although there is no consistency in studies regarding the mechanism of action." (PMID 38792644, 2024).
endometrial cancer (2 papers, 2020 to 2024). Primary or metastatic malignant neoplasm involving the endometrium (mucous membrane that lines the endometrial cavity). "For plasma proteins, a six-biomarker panel combining SERPINA4, APOA2, TTR, CRP, CLEC3B and APOD predicted advanced stage endometrial cancer with AUC 0.93 (0.85–0.99)." (PMID 38513301, 2024).
gestational diabetes (2 papers, 2023 to 2024). Carbohydrate intolerance first diagnosed during pregnancy. "The study in pregnant women with gestational diabetes revealed reduced APOA2 expression, indicating its involvement in inflammation." (PMID 38136890, 2023). "In women with gestational diabetes, APOA2 is significantly correlated with gestational age and may serve as a potential biomarker for preterm birth." (PMID 38177949, 2024).
Hepatitis (2 papers, 2013 to 2022). Inflammation of the liver. "Apolipoprotein A2 (Apo A2) suppressed ConA-induced hepatitis by inhibiting the phosphorylation of ERK1/2 and cjun and reduced the intra-hepatic infiltration of inflammatory cells." (PMID 24171052, 2013).
Hypertension (2 papers, 2012 to 2019). The presence of chronic increased pressure in the systemic arterial system. "CYP3A4, APOA2, PPARG, ALOX, and CYP4F2, proteins related to lipid homeostasis affect the occurrence of hypertension, and PTGER2, ALOX5, LTF, ITGB, and GATA3 relate to the inflammatory and immune response in glomeruli." (PMID 30809144, 2019).
intraductal papillary mucinous neoplasm (2 papers, 2015 to 2023). "The findings of a retrospective study indicate that low serum levels of APOA2-ATQ/AT can be a potential biomarker for identifying intraductal papillary mucinous neoplasm (IPMN) patients at high risk of developing PDAC." (PMID 38067270, 2023).
liver fibrosis (2 papers, 2013 to 2025). "These investigators also observed significant regulation of ApoA2, A4 and A4 precursor in NAFLD and various degrees of liver fibrosis." (PMID 24070255, 2013).
Renal amyloidosis (2 papers, 2020 to 2022). A form of amyloidosis that affects the kidney. "The mutation of human APOA2 is associated with systemic deposition disease, such as renal amyloidosis or cardiomyopathy with atrial fibrillation." (PMID 35629966, 2022). "Limited human data suggest that ApoA2 is implicated in renal amyloidosis." (PMID 32830851, 2020).
sarcopenia (2 papers, 2022 to 2024). Progressive decline in muscle mass due to aging which results in decreased functional capacity of muscles. "Moreover, P11597 (CETP) and P02652 (APOA2) were involved in multiple biological processes, suggested that these two proteins played an important role in the progression of sarcopenia and had potential diagnostic value." (PMID 36192674, 2022). "In addition, the diagnostic value of CETP and APOA2 in sarcopenia and whether they could be used as therapeutic targets need further research." (PMID 36192674, 2022). "In conclusion, our study provided a serum proteomic profile of sarcopenia patients, and identified two proteins (CETP and APOA2) with diagnostic value." (PMID 36192674, 2022). "The PPI network further suggested that the cholesteryl ester transfer protein and Apolipoprotein A2 could serve as biomarkers to facilitate diagnosis of sarcopenia." (PMID 36192674, 2022). "In contrast to CETP, the level of APOA2 was down-regulated in early sarcopenia OAs group." (PMID 36192674, 2022). "Furthermore, the nature of the cross-sectional study was unable to determine a causal relationship between APOA2, CETP and sarcopenia." (PMID 36192674, 2022).
varicocele (2 papers, 2020 to 2024). A condition characterized by the dilated tortuous veins of the spermatic cord with a marked left-sided predominance. "In males with varicocele-related infertility, APOA2 has been associated with testicular oxidative stress and sperm function, and its expression was significantly downregulated in the seminal plasma of patients with varicocele." (PMID 39765560, 2024).
ameloblastoma (1 paper, 2022). The most common odontogenic tumor, arising from the epithelial component of the embryonic tooth and usually affecting the molar-ramus region of the mandible or maxilla. "With these bioinformatic analyses it is possible that pathogenic ameloblastoma development involve these genes in intracellular regulation (AKT1, ACTC1, ADAM10, and APOA2) or for tumor microenvironment regulation (CRP, BCHE, APP, AGT)." (PMID 36553196, 2022).
ANCA-associated vasculitis (1 paper, 2022). "This was in line with previously reported beneficial effects of anti-ApoA2, such as effective recovery from renal disorders and decreased levels of MPO-ANCA and inflammatory cytokines in SCG/Kj mice models of MPO-ANCA-associated vasculitis (MAAV)." (PMID 36550471, 2022).
Cachexia (1 paper, 2024). Severe weight loss, wasting of muscle, loss of appetite, and general debility related to a chronic disease. "Significant co-upregulation of APOA2 and PAX7 was found in Black patients with localized disease, both linked to cachexia." (PMID 39580376, 2024).
cardiomyopathy (1 paper, 2023). A disease of the heart muscle or myocardium proper. "An upregulated expression of Apoa2 in cardiomyopathy was reported." (PMID 37511084, 2023).
cataract (1 paper, 2021). Partial or complete opacity of the crystalline lens of one or both eyes that decreases visual acuity and eventually results in blindness. "Conversely, female POAG patients had significantly greater levels of APOA1 (FC = 1.36; p < 0.01), APOA2 (FC = 1.21; p = 0.03), APOA4 (FC = 1.30; p = 0.04), APOC3 (FC = 1.38; p = 0.01), and APOD (FC = 1.20; p = 0.04) compared to cataract patients." (PMID 34602085, 2021).
cholestasis (1 paper, 2024). Impairment of the bile flow caused by obstruction within the liver, or outside the liver in the bile duct system. "Given the pivotal role of PPARα in liver lipid homeostasis and the treatment of fenofibrate, severe as a PPARα agonist, against cholestasis-induced hepatic injury, the expression of APOA2 and PPARα was detected by western blotting to verify the relationship between ICP and control groups." (PMID 38177949, 2024).